GLI2 (GLI family zinc finger 2)
Description:
Transcription factor that acts as a key effector of the smoothened signaling pathway, and which plays a role in skeleton development. Specifically binds to the minimal GLI-consensus sequence 5'-GACCACCCA-3' to activate or repress the expression of target genes (By similarity). Functions both as a transcriptional activator and repressor: the full-length GLI2 form (Transcription activator GLI2) acts as a transcription activator following smoothened activation, while the Transcription repressor GLI2R, which is generated in absence of smoothened, acts as a transcription repressor (By similarity). The transcriptional activator form constitutes the major form of GLI2 (By similarity). [Transcription activator GLI2]: Transcription factor, which activates expression of target genes in response to smoothened (SMO) activation. Constitutes a major form of GLI2, while the transcription repressor form (GLI2R) plays a minor role (By similarity). [Transcription repressor GLI2R]: Transcription repressor, which inhibits expression of target genes in the absence of smoothened (SMO) signaling (By similarity). Generated by proteolytic processing of the full-length GLI2 form in the absence of hedgehog (DHH, IHH or SHH), when SMO transducer is inhibited (By similarity). Constitutes a minor form of GLI2, while the transcription activator GLI2 form plays a major role in smoothened signaling (By similarity). [Isoform 1]: Involved in the smoothened (SHH) signaling pathway. [Isoform 2]: Involved in the smoothened (SHH) signaling pathway. [Isoform 3]: Involved in the smoothened (SHH) signaling pathway. [Isoform 4]: Involved in the smoothened (SHH) signaling pathway. [Isoform 5]: Acts as a transcriptional repressor. [Isoform 1]: (Microbial infection) Acts as a transcriptional activator in T-cell leukemia virus type 1 (HTLV-1)-infected cells in a Tax-dependent manner. Binds to the DNA sequence 5'-GAACCACCCA-3' which is part of the Tax-responsive element (TRE-2S) regulatory element that augments the Tax-dependent enhancer of HTLV-1. [Isoform 2]: (Microbial infection) Acts as a transcriptional activators in T-cell leukemia virus type 1 (HTLV-1)-infected cells in a Tax-dependent manner. Binds to the DNA sequence 5'-GAACCACCCA-3' which is part of the Tax-responsive element (TRE-2S) regulatory element that augments the Tax-dependent enhancer of HTLV-1. [Isoform 3]: (Microbial infection) Acts as a transcriptional activators in T-cell leukemia virus type 1 (HTLV-1)-infected cells in a Tax-dependent manner. Binds to the DNA sequence 5'-GAACCACCCA-3' which is part of the Tax-responsive element (TRE-2S) regulatory element that augments the Tax-dependent enhancer of HTLV-1. [Isoform 4]: (Microbial infection) Acts as a transcriptional activators in T-cell leukemia virus type 1 (HTLV-1)-infected cells in a Tax-dependent manner. Binds to the DNA sequence 5'-GAACCACCCA-3' which is part of the Tax-responsive element (TRE-2S) regulatory element that augments the Tax-dependent enhancer of HTLV-1.
Synonyms: THP2; HPE9; THP1; CJS; PHS2
Tractability: Small molecule: it belongs to a druggable protein family. PROTAC: UniProt records ubiquitination sites on it; ubiquitination databases record sites on it; a small molecule that binds it is known.
Target class: Transcription factor
Gene: Protein-coding gene on chromosome 2 (120,735,623 to 120,992,653, forward strand). Ensembl gene ENSG00000074047.
Subcellular location: Nucleus; Cytoplasm; Cell projection, cilium; Nucleus (Transcription activator GLI2); Nucleus (Transcription repressor GLI2R); Nucleus (Isoform 1); Nucleus (Isoform 2)
Subcellular location (Human Protein Atlas): Nucleoli; Basal body; Centrosome; Nucleoplasm
Pathways (Reactome):
Signal Transduction: Degradation of GLI2 by the proteasome; GLI proteins bind promoters of Hh responsive genes to promote transcription; Hedgehog 'off' state; Hedgehog 'on' state
Gene expression (Transcription): RUNX2 regulates chondrocyte maturation
Gene Ontology:
Molecular function: DNA-binding transcription activator activity, RNA polymerase II-specific; promoter-specific chromatin binding; protein binding; sequence-specific DNA binding; sequence-specific double-stranded DNA binding; zinc ion binding; DNA-binding transcription factor activity, RNA polymerase II-specific; RNA polymerase II cis-regulatory region sequence-specific DNA binding; double-stranded DNA binding; RNA polymerase II transcription regulatory region sequence-specific DNA binding
Biological process: hair follicle morphogenesis; negative regulation of transcription by RNA polymerase II; positive regulation of DNA replication; positive regulation of DNA-templated transcription; positive regulation of transcription by RNA polymerase II; smoothened signaling pathway; axon guidance; branching morphogenesis of an epithelial tube; cerebellar cortex morphogenesis; developmental growth; embryonic digestive tract development; floor plate formation; heart development; hindbrain development; hindgut morphogenesis; kidney development; lung development; mammary gland development; neuron development; odontogenesis of dentin-containing tooth; osteoblast development; pattern specification process; pituitary gland development; positive regulation of T cell differentiation in thymus; proximal/distal pattern formation; and 9 more
Cellular component: centrosome; ciliary basal body; non-motile cilium; nucleolus; nucleoplasm; nucleus; ciliary base; ciliary tip; cilium; cytosol; cytoplasm
Genetic constraint (gnomAD): Loss-of-function variants: 20 observed, 79.78 expected, observed/expected ratio (o/e) 0.25, 90% interval 0.17 to 0.36. The upper end of that interval is the gene's LOEUF score, 0.36, which puts it in group 1 of 6, group 1 being the genes least tolerant of losing a copy. Missense variants: 2,014 observed, 2,076.6 expected, observed/expected ratio (o/e) 0.97, 90% interval 0.93 to 1.01. Synonymous variants: 939 observed, 894.19 expected, observed/expected ratio (o/e) 1.05, 90% interval 0.99 to 1.11.
Homologues: Orthologues: chimpanzee GLI2 (99% identical), macaque GLI2 (97% identical), guinea pig GLI2 (86% identical), pig GLI2 (86% identical), rabbit GLI2 (86% identical), mouse Gli2 (83% identical), dog GLI2 (77% identical), zebrafish gli2a (53% identical), zebrafish gli2b (46% identical). Paralogues in human: GLI3 (45% identical), GLI1 (27% identical), GLIS3 (16% identical), GLIS1 (14% identical), GLIS2 (12% identical), ZIC2 (11% identical), ZXDC (11% identical), ZIC1 (10% identical), ZIC3 (10% identical), ZIC5 (10% identical), ZXDA (9% identical), ZXDB (9% identical), and 2 more.
Diseases named in the same sentence as GLI2 in open-access papers:
GLI2 is named in the same sentence as 250 diseases in open-access papers, as found by Europe PMC text mining. Sharing a sentence is not in itself a finding about the gene and the disease. The quoted sentences say what the papers report.
breast carcinoma (66 papers, 2010 to 2026). "On the contrary, increased expression of GLI2 was linked to various microRNAs in numerous cancers, including breast cancer." (PMID 38474826, 2024). "In conclusion, SETDB2 interacts with ΔNp63α, methylates and stabilizes ΔNp63α to upregulate the transcription of the Hedgehog signaling pathway-associated genes CXCR4, PTCH1 and GLI2, which promote breast cancer stem cell maintenance and tumor initiation." (PMID 32549764, 2020). "BCAR4 was originally found associated with tamoxifen resistance in breast cancer, in which it likely mediated the function through activating GLI2 signaling." (PMID 30513511, 2018). "In addition to PTCH1, high SHH, SMO, GLI1, and GLI2 expression levels were all associated with a poor prognosis in breast cancer patients." (PMID 36142286, 2022). "Human epidermal growth factor receptor 2 (HER2) -mediated GLI2 stabilization promotes anoikis resistance and metastasis of breast cancer cells." (PMID 38498906, 2024). "The basal expression levels of GLI1 and GLI2 downstream of the Hh ligand in TNBC are higher than those in hormone receptor-positive (HR+) breast cancer, and the prognosis of breast cancer patients with high GLI1 expression is poor." (PMID 37700593, 2023). "First, we analyzed the expression of SHH, PTCH1, SMO, GLI1, and GLI2 in normal breast and breast cancer tissues through the Oncomine database." (PMID 36142286, 2022). "TNBC has higher basal expression levels of the Hh signaling pathway gene such as GLI1 and GLI2, which are downstream of Hh ligands, than other breast cancers." (PMID 35744786, 2022). "BCAR4, which has a crucial role in tamoxifen-resistance breast cancer, can bind to the promoter region of GLI2 and activate the GLI2 downstream genes, making the prostate cancer cells less sensitive to androgen stimulation." (PMID 34103477, 2021). "Many studies support the claim that target genes GLI1 and GLI2 are involved in breast cancer cell proliferation, survival, migration, invasion, EMT, angiogenesis, and osteolytic metastasis." (PMID 31979397, 2020). "It was recently shown that targeting Gli2 inhibition to the tumor-bone microenvironment effectively reduced TIBD in a model of breast cancer metastasis to bone." (PMID 32967150, 2020). "Recently, it has been found that FOXC1 directly activates the transcription of GLI2-mediated SHH targets in human basal-like breast cancer cells by binding and acting as a co-factor to GLI2, bypassing SMO." (PMID 30073412, 2019). "Expression of FOXC1 was significantly correlated with that of Gli2 and its downstream targets in breast cancers." (PMID 29552326, 2018). "BCAR4 has been shown binding to the promoter of GLI2 to activate GLI2 signaling pathways in breast cancer cells, and in osteosarcoma cells." (PMID 30513511, 2018). "Expression of FOXC1 was correlated with Gli2 expression and its downstream targets in breast cancers." (PMID 29552326, 2018). "In a breast cancer model, tumor cell growth and self-renewal properties were modulated by p63-driven induction of Shh, Gli2, and Ptch expression." (PMID 26988232, 2016). "Among these, GLI1 and GLI2 have been thought to be crucial for the development and progression of many types of human cancers, including lung, pancreatic, prostate, and breast cancer." (PMID 26413813, 2015). "Once formed, Smad2/3:Gli2 complexes stimulate the expression of parathyroid hormone-related protein necessary for breast cancer metastasis to bone." (PMID 26160166, 2015). "These evidences indicated that, in addition to CXCR4, the expression of CXCR7 and LCP1 was also in the downstream of GLI1 and GLI2 in breast cancer cells." (PMID 26413813, 2015). "Hedgehog pathway members PTCH, Gli-1, and Gli-2 have been reported to be more highly expressed in normal mammary stem cells and their malignant counterparts, breast cancer stem cells, compared to more differentiated breast cancer cells." (PMID 25276795, 2014).
breast carcinoma (continued). "In osteolytic breast cancer cells, Gli2 has been shown to regulate the expression of parathyroid hormone related protein (PTHrP), a major osteolytic factor." (PMID 22096521, 2011). "Analysis of several breast cancer cell lines revealed the co-expression of Gli-2 and SLUG in only breast cancer cell lines with CD44+/CD24- phenotype." (PMID 20691079, 2010). "GLI family zinc finger 2 (GLI2), a transcription factor in the Hedgehog signaling pathway, controls genes linked to cell proliferation, metastasis, therapy resistance, and stem cell maintenance in breast cancer." (PMID 41019507, 2026). "For instance, ADGRG6 promotes breast cancer growth upon progesterone stimulation, serves as a mutation marker for bladder cancer recurrence and immunotherapy monitoring, and drives colorectal cancer proliferation via HDAC2 and GLI2 signaling." (PMID 41614755, 2025). "Furthermore, NF-B induced the transcription factor Forkhead Box C1 (FOXC1), which is an upstream mediator of Hh signaling via upregulation of GLI2 expression in basal-like breast cancer cells." (PMID 35744786, 2022). "Thus, the Hedgehog signaling pathway and its core members, such as SHH and GLI2, play an essential role in the growth regulation of breast cancer." (PMID 36142286, 2022). "Therefore, we used the Kaplan–Meier plotter website to analyze the effects of SHH, PTCH1, SMO, GLI1, and GLI2 on the prognosis of breast cancer patients." (PMID 36142286, 2022). "Additionally, the Forkhead Box C1 (FOXC1) transcription factor, an upstream mediator of Hh signaling via upregulation of GLI2 expression in basal-like breast cancer cells is induced by NF-κB." (PMID 31394751, 2019). "TGF-β induces Gli1 and Gli2 in a Smad3-dependent manner in epithelial and mesenchymal cell lines, dermal fibroblasts, osteolytic Langerhans cells, breast carcinoma cells, and pancreatic ductal adenocarcinoma cells." (PMID 31297044, 2019). "Furthermore, blocking HH signaling in metastatic breast cancer cells with the repressor form of GLI2 reduces endogenous and TGF-β-stimulated PTHrP expression and bone metastasis in mice, supporting the role of GLI2 downstream of TGF-β in driving metastasis." (PMID 31244888, 2019). "In particular, TGF-β may induce GLI1 expression in a GLI2-dependent manner independently from SMO in breast cancer." (PMID 29456503, 2017). "Notably, in tumor-bearing mice, MDSCs in bone marrow exhibit increased expression of TGF-β1 that stimulates breast cancer cells to express certain factors e.g., parathyroid hormone-related protein (PTHrP) and GLI2 that are essential for breast cancer-induced osteolysis." (PMID 39497943, 2024). "Additionally, activation of Gli2 and Gli2 is dependent on SMAD3 in several cell lines including keratinocytes and breast carcinomas, and activation of the Gli2 target gene PTHLH (encoding parathyroid hormone-related protein) occurs independently of canonical Hh signaling." (PMID 37954979, 2023). "Another study proved that upregulated lncRNA breast cancer anti-estrogen resistance 4 (BCAR4) in triple negative breast cancer is transcriptionally targeted by Yes-associated protein (YAP) and it is required for YAP-promoted glycolysis through GLI2-dependent Hedgehog signaling." (PMID 33652661, 2021). "In breast cancer, the activation of the pathway in CSCs expressing GLI1 or GLI2 through Hh ligands or inhibition of GLI1 or GLI2 using cyclobutrazine or siRNA results in a change in BMI-1 expression." (PMID 40034124, 2025). "Using qRT-PCR, we validated this proposed downregulation with the experimental detection of decreases in GLI2 and WNT4 mRNA levels following 9 days of 15 μM RSV treatment in MCF-7 and MCF10CA1a breast cancer cells." (PMID 38474826, 2024). "We found that normal breast tissue and breast cancer tissue expressed significantly different levels of SHH, PTCH1, SMO, GLI1, and GLI2 (p < 0.05)." (PMID 36142286, 2022).
breast carcinoma (continued). "Their expression levels were all higher in breast cancer tissue than in normal breast tissue, with more than a two-fold difference for SMO, GLI1, and GLI2." (PMID 36142286, 2022). "In support of this, FOXC1 enhanced the DNA-binding ability of GLI2, evident by enhanced binding of GLI2 at the promoter of FAM38B gene, which is also markedly upregulated in breast cancer cells as a result of FOXC1 overexpression." (PMID 34572373, 2021). "Comprehensive RNA sequencing data collected as a part of the MET500 cohort was analyzed for gene expression of Gli2, PTHLH, ITGB1, and ITGA2 in metastatic breast cancer samples." (PMID 34199096, 2021). "Recently, studies of estrogen receptor (ER)-positive breast cancer (BC) cell lines have revealed that estrogen can increase GLI1 and GLI2." (PMID 31979397, 2020). "In a metastasis model of breast cancer cells MDA-MB-231, SMO-independent induction of GLI2 is required for TGF-β to stimulate the expression of parathyroid hormone-related protein (PTHrP), an important osteolytic factor in bone metastasis." (PMID 31244888, 2019). "The ΔNp63 isoform of p63, which is the predominant isoform expressed in mammary epithelium, maintains the multipotent stem cell population in normal epithelium as well as in breast cancer; ΔNp63 drives expression of Hh ligands, PTCH1, GLI1 and GLI2." (PMID 31394751, 2019). "In breast cancer cells, long non-coding RNA breast cancer anti-estrogen resistance 4 (BCAR4) coordinates with the GLI2-dependent Hedgehog signaling to mediate YAP-induced glycolysis, and forms a YAP-BCAR4/GLI2-glycolysis axis." (PMID 30176928, 2018). "In breast cancer, TGF-β signaling was shown to activate GLI2 target genes culminating in enhanced bone metastasis." (PMID 26988232, 2016). "An additional pathway that can interact with HH signaling in breast cancer is TGFβ, which induces transcriptional up-regulation of GLI1 and GLI2." (PMID 27548161, 2016). "In breast cancer cells, we found that GLI1 and GLI2 up-regulated these expressions, while treatment with GLI-specific inhibitor GANT61 reduced the expressions." (PMID 26413813, 2015). "In order to explore the effects of SU6668 on regulation of GLI2 in the context of TGF-β pathway, immortalized breast cancer cells MDA-MB-231 were used." (PMID 24418624, 2014). "In various cancer models—breast cancer cells, gastric cancer cells, medulloblastoma —CUR has been shown to inhibit the Hh pathway by downregulating the expression of SHh, PTCH1, and GLI1/GLI2." (PMID 39457084, 2024). "Notably, EMT and stemness genes such as ZEB2, SNAIL, TWIST, Gli2, WNT, and AKT3, which are overexpressed in basal-like breast cancer (BLBC), were significantly upregulated in drug-resistant cells." (PMID 38078907, 2023). "The database analysis of the Hedgehog pathway markers (SHH, PTCH1, SMO, GLI1, and GLI2) revealed that the Hedgehog pathway is activated in breast cancer tissues, and its high expression is not conducive to a patient’s survival." (PMID 36142286, 2022). "Interestingly, in highly metastatic MDA-MB-231 breast cancer cells, β–catenin/TCF-4 was shown to stimulate GLI2 promoter activity by binding to TCF-binding element (TBE) within the promoter but only in the presence of active functioning TGF-β/SMAD signaling." (PMID 34572373, 2021). "Similarly, an analysis of breast cancer samples from the TCGA database and Curtis dataset also revealed a strong correlation between FOXC1 and GLI2." (PMID 34572373, 2021). "Besides MYC itself, we find upregulation of other breast cancer stem cell factors (SOX2, SOX18, THY1, EYA1, GLI2, SALL1, GLIS1, CXCR4), suggesting that MYC HME cells adopt a stem-like state." (PMID 31942031, 2020). "This is consistent with previous reports that identified overexpression of SMO and GLI2 in progesterone receptor (PR) negative breast cancers and gastric cancers." (PMID 32784501, 2020).